CRP (C-reactive protein)
Diseases named in the same sentence as CRP in open-access papers (continued):
Sharing a sentence is not in itself a finding about the gene and the disease.
COVID-19 (continued). "Regarding the laboratory data reported in our study, a significantly high NLR, CRP, LDH, and ferritin in addition to D dimer were reported among COVID-19 cases compared to controls." (PMID 39452786, 2024). "Parameters including SpO2, CRP, ALT, AST, D-dimer levels, and the chest CT score demonstrate good discriminatory power between co-infected individuals and those with COVID-19 alone." (PMID 38793006, 2024). "Several systematic reviews and meta-analyses confirmed the predictive value of inflammatory markers, especially CRP and PCT, in COVID-19." (PMID 39408623, 2024). "For these COVID-19 convalescents, we found higher plasma concentrations of CRP, SAA1, and SAA2 six months after COVID-19." (PMID 39183264, 2024). "Clinical benefits were also observed in outcomes related to inflammation, such as C-reactive protein and TNF-alpha, in COVID-19 patients (critically low quality)." (PMID 39360254, 2024). "After Cox regression adjustment, Presepsin, qSOFA, NEWS2, PSI, CURB-65, CRP, NLR, CAR, and LCR were identified as independent predictors of 28-day mortality in COVID-19 patients (all p-values < 0.05)." (PMID 38671532, 2024). "We found that our COVID-19+ cohort had higher neutrophil counts, NLR, monocyte counts, CRP levels and a lower CD8 count compared to the control cohort, which is consistent with existing data." (PMID 38715114, 2024). "Only levels of CRP and LDH at baseline were significantly higher in the severe COVID-19 group compared to the mild COVID-19 (p ≤ 0.01)." (PMID 39691720, 2024). "Although there are potential host and pathogen response differences for PCT and CRP in the presence of LMIC geographical specific endemic infections, this is unlikely to dramatically influence their dynamics in the context of COVID-19." (PMID 39290622, 2024). "On multivariable analysis, COVID-19 severity was an independent predictor of mortality (OR10; 95%CI 1.62-67.19) after adjustment for age, gender, diabetes mellitus, C-reactive protein, serum Ferritin, Procalcitonin, and Fibrinogen values, and prior or new MI." (PMID 39697349, 2024). "The present study also points to the modification of inflammatory markers in COVID-19/PCI, as well as to the high values of the average concentrations for serum CRP and LDH in patients with chronic respiratory diseases, especially asthma and COPD." (PMID 38392603, 2024). "Our study explored the impact of COVID-19 and other pathogens affected PCT and CRP in sepsis patients." (PMID 38172766, 2024). "One study demonstrated that increased neutrophil, CRP, procalcitonin, AST, ALT, and total BIL values and decreased lymphocytes, platelets, and albumin values have a prognostic value for COVID-19." (PMID 39473741, 2024). "COVID-19 cases had significantly higher neutrophil/lymphocyte ratio (NLR), CRP, ferritin, LDH, significantly lower red blood cells (RBCs), hematocrit (HCT), platelets, and relative and absolute lymphocytic and neutrophilic counts." (PMID 39452786, 2024). "Inflammatory markers, among others C-Reactive Protein (CRP) and erythrocyte sedimentation rate (ESR), can predict disease progression and clinical outcomes, being critical in COVID-19 management." (PMID 39685703, 2024). "There appears to be a positive link between inflammation biomarkers such as CRP, ferritin, and LDH and the number of comorbidities in COVID-19 patients." (PMID 38610602, 2024). "Among COVID-19 pregnant patients AST, ALT and GGT > URL were positively correlated with inflammatory parameters (PCT, CRP and IL-6) and negatively with white blood count." (PMID 38166966, 2024). "In moderate COVID-19 patients, IGFBP-2 levels were positively correlated with CRP, procalcitonin, LDH, AP, and IL-6, and negatively correlated with lymphocyte count." (PMID 38255230, 2024).
COVID-19 (continued). "The relationship between the severity of COVID-19, patient outcomes, and the values and dynamics of biomarkers such as leukocytes, neutrophil-to-lymphocyte ratio (NLR), CRP, ASAT, LDH, D-dimers, ferritin, and IL-6 has been demonstrated in numerous studies." (PMID 39767597, 2024). "Inflammatory markers, notably C-reactive protein (CRP), interleukin-6 (IL-6), and erythrocyte sedimentation rate (ESR), have a positive correlation with COVID-19 severity." (PMID 38800223, 2024). "EAT volume has a positive correlation observed with the parameters of CRP and LDL-C in our COVID-19 subjects, which agrees with observations from previous studies of coronary heart disease populations." (PMID 38706946, 2024). "A recent study has documented variances in CRP levels among patients afflicted with FluA, RSV, and COVID-19, suggesting its usefulness in evaluating the different levels of inflammatory response in these three diseases." (PMID 39066228, 2024). "Our findings revealed that COVID-19 patients in the ICU had significantly higher levels of ferritin, hepcidin, zinc, CRP, and IL-6 compared with the other two study groups in both geographic regions." (PMID 39062181, 2024). "The production of CRP by hepatocytes is stimulated by cytokines like interleukin‐6 (IL-6) and tumor necrosis factor-α (TNF-α) during COVID-19 development." (PMID 38184750, 2024). "COVID-19 vaccination generally improves LDH, CRP, and D-Di levels, particularly in immunocompromised patients, supporting vaccination efforts." (PMID 39712749, 2024). "Lymphopenia, ferritin, CRP, lactate dehydrogenase (LDH), and D-dimer elevation are widely recognized as poor prognostic factors in the general population of COVID-19 patients." (PMID 39452485, 2024). "Few studies describe the differences between patients with acute SARS-CoV-2 infections and patients with PIMS-TS, where CRP elevation and reduced platelet count were more pronounced in PIMS-TS than in acute COVID-19 patients." (PMID 38892153, 2024). "The correlation of aldosterone, urea, creatinine, C-reactive protein (CRP), and procalcitonin (PCT) levels with 28 days of mortality in patients treated for COVID-19 were performed." (PMID 38570550, 2024). "We observed that CRP was positively correlated with the OxLDL/LDL-C ratio and OxLDL in COVID-19 patients, suggesting consistency between lipoprotein oxidative damage and inflammation." (PMID 39628680, 2024). "Biomarkers and enzymes, such as CRP, ALT, and AST are other factors in the clinical course of COVID-19." (PMID 38690274, 2024). "Based on the available evidence, the evaluation of WBC, CRP, ESR, and AST levels in children with COVID-19 is an critical predictor for hospitalization as well as determining the severity of the infection." (PMID 38404412, 2024). "CRP and IL6 were the biomarkers with the highest discriminatory capacity for hospitalization, and severe COVID-19, respectively." (PMID 39664394, 2024). "We measured weekly concentrations of vitamins A, B6, D, and E; iron; zinc; copper; selenium; and CRP as a marker of inflammation state and the SOFA score indicating disease severity in 20 critically ill COVID-19 patients during three weeks of ICU stay." (PMID 38337670, 2024). "COVID-19 disease severity was linked to multiple hematological markers (lymphopenia, thrombocytopenia, neutrophilia) and inflammatory markers (CRP, IL-6, ferritin), providing a rationale for research on PTX in COVID-19, as it affects many of those markers." (PMID 39446164, 2024). "More importantly, multivariate analyses identified age, CRP, ferritin, and SIRI as independent predictors of the need for advanced respiratory support in hospitalized COVID-19 patients." (PMID 39149665, 2024). "The findings of our study indicate that severe COVID-19 patients have higher INR (coagulation biomarker), creatinine (renal injury biomarker), CRP and PCT (inflammation biomarkers), and fibrinogen (coagulation biomarker) compared to the moderate group." (PMID 39408623, 2024).
COVID-19 (continued). "A high frequency of AKI was documented in COVID-19 patients, with several predictors: age, male sex, DM, CKD, CRP, ICU admission, and vasopressor support." (PMID 38078832, 2024). "The lymphocyte count, C-reactive protein, lactate dehydrogenase, D-dimer, albumin and DAR were likely to influence the capacity to predict adverse outcomes of COVID-19 patients." (PMID 39144651, 2024). "In summary, the study found that elevated LDH, ferritin, and D-dimer levels were reliable biomarkers for predicting COVID-19 severity and prognosis, while the role of CRP and PCT in COVID-19 pathogenesis requires further investigation." (PMID 39195007, 2024). "We observed higher ferritin and CRP levels, along with lower DBP, TnT, and D-dimer levels, in patients with COVID-19." (PMID 39139171, 2024). "The biomarkers CRP, IL6, IP10, IL8, IL1RA, and suPAR showed good individual prognostic performance for severe COVID-19." (PMID 39664394, 2024). "The aim of this study was to analyze the potential relationship between the level of selected cytokines (IL-6, IL-10, IL-12, IL-15, TNF-α) and inflammatory markers (CRP, NLR, PLR, LMR, SII) and the duration of rehabilitation in patients after COVID-19." (PMID 39335569, 2024). "Consistent with the inflammatory nature of COVID-19, patients with HCM and COVID-19 had higher peak inflammatory tone, defined by CRP." (PMID 38667722, 2024). "Certain parameters like SpO2, CRP, ALT, AST, and D-dimer effectively differentiate between co-infected and COVID-19 patients." (PMID 38793006, 2024). "Predictors of death from COVID-19 in ESKD patients include old age, multimorbidity, decreased eosinophils, increased C-reactive protein, raised D-dimer, and increased lactate dehydrogenase." (PMID 38807735, 2024). "UIBC, TIBC, hepcidin/CRP, and hepcidin/IL-6 were lower, and IRF, ferritin/hepcidin, and hepcidin/iron were higher in severe and critical COVID-19 than in mild and moderate COVID-19." (PMID 38892911, 2024). "Laboratory findings from a retrospective study of COVID-19 patients in China demonstrated a decrease in the albumin and lymphocyte count and an elevation in the WBC count, ALT, AST, LDH, CRP, and serum creatinine." (PMID 39995847, 2024). "Therefore, in addition to a preexisting proinflammatory response and superimposed hospital-acquired infections, COVID-19 patients with higher levels of CRP and PCT may be preferred to maintain sharp vigilance for the occurrence of diabetes-related hyperglycemic emergencies." (PMID 38455656, 2024). "Elevated levels of inflammatory markers, such as C-reactive protein (CRP), have also been observed in individuals with COVID-19, as well as changes in renal markers due to the high expression of ACE2 in glomerular cells." (PMID 38398867, 2024). "There were statistically significant correlations between CTSS, neutrophil-to-lymphocyte ratio (NLR), CRP, D-dimer, and LDH levels among COVID-19 patients." (PMID 38361692, 2024). "Results of 855 patients in the training cohort showed that CRP, A/G, NLR, INR, BUN were predictive factors for clinical deterioration of COVID-19." (PMID 37122321, 2023). "In a study of 172 COVID-19 hospitalized patients, a significant correlation between CD8+ T cells and inflammation markers such as CRP and Neutrophil to Lymphocyte ratio (NLR) was observed." (PMID 36986336, 2023). "Many studies have found significant correlations between higher CRP levels and complications such as acute lung injury (ALI), acute respiratory disorder stress (ARDS), and mortality in COVID-19 patients." (PMID 38027038, 2023). "In the case of patients diagnosed with moderate and severe forms of COVID-19, the variation in biological tests showed high concentrations for serum glucose, LDH, and CRP." (PMID 38248722, 2023).
COVID-19 (continued). "Serum levels of lactate dehydrogenase (LDH), C-reactive protein (CRP), and D-dimer are routinely tested in hospitalized COVID-19 patients to assess acute inflammation, blood clotting tendencies, and increased tissue damage, respectively." (PMID 37509430, 2023). "The determination of cut-off values for continuous variables (sepsis biomarkers) in this research (MDW, CRP, PCT, lactate) was based on related literature and clinical experience in dealing with critically ill COVID-19 patients." (PMID 36769843, 2023). "According to the results of any previous studies, IL-6 as a potent proinflammatory cytokine can stimulate c-reactive protein (CRP) and has been introduced as a trigger of the cytokine storm in COVID-19." (PMID 37161412, 2023). "Recently, multiple studies have shown that the inflammatory markers CRP, PCT, leukocytes, and IL-6 are important predictors of mortality in COVID-19, too." (PMID 37386635, 2023). "IgG, IL-6, CRP, NLR, PLR, glucose, AST, urea, creatinine, and eGFR were significantly higher in severe/critical COVID-19 patients." (PMID 36838284, 2023). "For the COVID-19 patients, correlation analyses were conducted to determine whether these textural and histogram features correlated with key laboratory test indices, including blood oxygen levels, white blood cell counts, lymphocyte counts, neutrophil counts, and C-reactive protein levels." (PMID 37959377, 2023). "Difference in median levels of CRP, Ferritin, LDH and PaO2/FiO2 ratio across critically ill, COVID-19 patients on mechanical ventilation with different demographic and clinical characteristics (n =159)." (PMID 37936743, 2023). "Compared to other inflammatory markers including CRP, ferritin, and D-dimer, GDF-15 was more sensitive and specific in diagnosing the early stage of COVID-19 severity and admission to the ICU in seriously afflicted COVID-19 patients." (PMID 37974205, 2023). "IL-6, CRP, NLR, PLR, glucose, AST, urea, creatinine, and eGFR were significantly higher in our severe/critical COVID-19 patients." (PMID 36838284, 2023). "Consistently, 3-doses of COVID-19 vaccine demonstrated a more effective and sustained promoting effect on circulating EOS, along with the attenuated inflammatory response (CRP)." (PMID 37217986, 2023). "Patients generally showed elevated levels of inflammatory markers including CRP and ESR concomitant with elevated serum ferritin; D dimer and procalcitonin levels, besides the COVID-19 characteristic lymphopenia and hypoxemia were also frequent." (PMID 37189123, 2023). "In particular, the 3rd booster shot of COVID-19 vaccine demonstrated a more effective and sustained promoting effect on EOS, while inhibiting the CRP level, both in the asymptomatic and mild patients." (PMID 37217986, 2023). "Laboratory workup revealed a normal complete blood, count and complete metabolic panel, c-reactive protein (CRP) was elevated at 13.5 mg/dL and COVID-19 polymerase chain reaction (PCR) was positive." (PMID 37193105, 2023). "Furthermore, the decrease in glutamine concentration in severe COVID-19 patients is positively correlated with lactate dehydrogenase, C-reactive protein, and pCO2 and positively correlated with pO2, disclosing formerly unknown consequences of low glutamine in severe COVID-19 pathologies." (PMID 37108759, 2023). "In a retrospective study of 514 COVID-19 patients, researchers found that BAR was a better predictor of mortality than CRP, procalcitonin, or LDH levels." (PMID 38074058, 2023). "Other non-specific biomarkers of COVID-19, such as the presence of neutrophilia, thrombocytopenia, hypoalbuminemia, elevation of liver enzymes and creatinine, as well as inflammatory markers, such as C-reactive protein (CRP) and interleukin 6 (IL-6), were also associated with a worse prognosis." (PMID 37109370, 2023). "Correlation analysis between galectin-3 and COVID-19 biomarkers showed a significant correlation with the serum levels of D-dimers, LDH, ferritin and CRP." (PMID 37958814, 2023).
COVID-19 (continued). "Applying PLS-DA and VIP scoring, we identified CRP elevation and reduced platelet numbers as laboratory parameters with the highest contribution to differentiating PIMS-TS from acute COVID-19." (PMID 38027272, 2023). "The present study highlights the consequential health effects of COVID-19 on adolescents with OWOB, including increased time in bed, sleep onset latency, and CRP and decreased in sleep efficiency." (PMID 38136035, 2023). "The aim of the present study was to examine whether Dipeptidyl-peptidase 3 (DPP3) and the inflammatory biomarkers IL-6, CRP, and leucocytes are associated with COVID-19 and able to predict the severity of pulmonary infiltrates in COVID-19 patients versus non-COVID-19 patients." (PMID 37733154, 2023). "The aim of our study was to evaluate the prognostic role of MDW, CRP, procalcitonin (PCT), and lactate in critically ill COVID-19 patients." (PMID 36769843, 2023). "Since the first AMI patient was treated with CRP-apheresis 8 years ago, it has been successfully and safely used in patients suffering from AMI, acute necrotizing pancreatitis, Crohn’s disease, COVID-19, stroke and after bypass surgery." (PMID 37626775, 2023). "As a secondary study objective, we also compared the performance of CRB-65 (a non-serum-based biomarker) against established serum inflammatory biomarkers of infection (C-reactive protein (CRP) and white cell count (WCC)) for prognosticating COVID-19 patients." (PMID 37760863, 2023). "The levels of PCT and the NLR were higher in the severe and critically ill patients and the levels of PCT, CRP, and the NLR had prognostic significance for COVID-19 mortality." (PMID 36983910, 2023). "Complete blood count (CBC), CRP, D-dimer, lactate dehydrogenase (LDH) and serum ferritin levels were measured for COVID-19 severity and complications." (PMID 37064327, 2023). "Since severe COVID-19 is characterised by increased C Reactive Protein (CRP) and lymphopenia, which were used in several COVID-19 clinical severity scores, we correlated the abundance of MCEMP1, ETS1 and HLA-DRA transcripts to CRP and lymphocyte counts." (PMID 36801619, 2023). "Lymphocyte counts, fibrinogen levels, and PaO2/FiO2 levels were significantly lower in patients with severe COVID-19, whereas WBC, NLR, LDH, CRP, D-dimer, PT, and ferritin values were significantly higher in those with severe disease." (PMID 37493737, 2023). "Demographic and clinical data on Hgb, CRP, and LDH levels; vaccination status in patients with COVID-19 and healthy volunteers." (PMID 36982882, 2023). "Moreover, COVID-19 complications such as bacterial coinfection (p < 0.001), anemia (p < 0.001), lymphopenia (p < 0.001), thrombocytopenia (p < 0.001), neutropenia (p = 0.007), high C-reactive protein (CRP) (p < 0.001), and increased lactate dehydrogenase (p < 0.001) negatively influenced survival." (PMID 38127882, 2023). "Recent studies show, in addition to wellknown factors such as IL-6, CRP, and ferritin, the NLR is also a valuable predictive factor for severe COVID-19." (PMID 37814623, 2023). "This can be explained that ESR, ASDAS-ESR, CRP, and ASDAS-CRP increased in post COVID-19 wave, whereas BASDAI slightly decreased during the COVID-19 wave, the major factor causing this result probably comes from the change of laboratory inflammatory index." (PMID 36611127, 2023). "COVID-19 patients with ESS had a significantly higher prevalence of severe events and had stronger inflammatory responses, with higher levels of CRP and erythrocyte sedimentation rate as well as a higher positive rate of procalcitonin." (PMID 37122395, 2023). "Studies have found increased inflammatory biomarkers, including those of C-reactive protein (CRP), erythrocyte sedimentation rate (ESR), and procalcitonin (PCT) in COVID-19 death cases." (PMID 37104352, 2023). "In our study of COVID-19 patients, MAX CRP levels were higher in those overweight or obese compared to normal or underweight patients, consistent with prior findings." (PMID 38003780, 2023).